IL10 (interleukin 10)
Diseases named in the same sentence as IL10 in open-access papers (continued):
Sharing a sentence is not in itself a finding about the gene and the disease.
infection (continued). "Conversely, concentrations of invasion-inhibitory factors including the hormone hCG and cytokine IL-10 were higher in serum from women with infection than in uninfected women (by 20%, P = .1 and by 340%, P = .08 respectively)." (PMID 23383132, 2013). "By 12h post-infection, all chemokines assessed in both IL-10-/- APC types were upregulated compared to B6 cells, indicating that Bb-elicited IL-10 does suppress chemokine production by both MØs and DCs." (PMID 24367705, 2013). "Infection of sst1S macrophages with C. pneumoniae resulted in a shift in the secreted cytokine profile towards enhanced production of interferon-β and interleukin-10, and induced apoptotic cell death, which was dependent on secretion of interferon-β." (PMID 24009502, 2013). "Membrane inserts were used to separate the monocyte and uroepithelial cell types during infection and revealed two synergistic IL-10 production effects based on contact-dependent and soluble interactions." (PMID 24155979, 2013). "In our studies, we found that CD4+ (Foxp3+ and Foxp3−) and CD8+ T cells, along with some NK cells and myeloid cells (CD11b+), were the major IL-10 producers early after infection." (PMID 23555256, 2013). "Very low levels of Leishmania-specific IL-10 were detected after the stimulation of spleen cells from vaccinated mice, 10 weeks after infection." (PMID 23573301, 2013). "Decreased or delayed IL-10 production results in severe tissue damage, a consequence of an uncontrolled inflammatory response, in a number of infections including T. gondii, Plasmodium spp." (PMID 23554169, 2013). "In contrast, ku80 infection was characterized by higher and lower expressions of TNFα and IL10, respectively." (PMID 24244155, 2013). "Across the sampling period, IL-10 levels remained similar at 0 and 2 week post infection (wpi), but increased in ConA + ES stimulated cultures at 4 and 6 wpi, and increased in Con A-stimulated cultures at 6 wpi." (PMID 23964850, 2013). "In infected BMDC, IL-10 was observed at 24 hours post-infection and in splenocytes kinetics of cytokine secretion was measured at 1, 2, 3 and 6 weeks postinfection." (PMID 24069337, 2013). "The level of IL-10 in the sera of nude mice was significantly higher than of scid mice at 43 days post infection (p.i.)." (PMID 23349889, 2013). "NDV increased DEX-induced IL-10 mRNA and protein expression by 7- and 3-fold, respectively, which was observed from 3 hours after infection." (PMID 23667643, 2013). "At day 28 post infection there was an increase in IL-10-producing cells in B6.CCR7-/- mice, which was also seen in CD8+ cells." (PMID 24205367, 2013). "In contrast, the IL-10 levels remained unaffected in B cell or T cell specific IL-10 knockouts on day 10 post infection." (PMID 24244162, 2013). "The concentrations of IFN-γ and IL-10 have been noted to increase in P. vivax-infected individuals during natural infection." (PMID 24354660, 2013). "In particular, the significant over-expression of the Csf1, Lefty1, Ccrl2, Gdf3, Il-10 and Ccl8 genes (1.8–5.8 fold increases) was seen at day 9 post-infection." (PMID 23861742, 2013). "H37Rv infection of DCs resulted in 3-fold increase in the production of IL-10 compared to uninfected DCs." (PMID 23762843, 2013). "On multivariate regression, comparing cytokine gene expression in health and infection, IL10 (P = 0.02), IL23 (P = 0.01), IL27 (P = 0.01), and TNFα (P = 0.03) were significantly different." (PMID 23935244, 2013). "For this purpose, we employed MCMV as an infecting agent, as infection of this virus enhanced DEX-induced IL-10 mRNA expression similar to NDV in DCs." (PMID 23667643, 2013). "This prompted us to concentrate further analysis of IL-10 producing cell populations on spleen of day two post infection." (PMID 24244162, 2013). "Along that line, a DC-based vaccination approach developed in our lab significantly reduced the antigen-specific production of IL-10 early after infection." (PMID 23825956, 2013).
infection (continued). "Despite the central role of IL-10 in suppressing T cell and macrophage activation within the granuloma, IL-10 neutralization or infection of IL-10 knockout (KO) mice results in only marginally reduced bacterial loads." (PMID 23420646, 2013). "Simultaneous expression of IFN-γ and IL-10 also has been reported after infection with porcine reproductive and respiratory syndrome virus." (PMID 24204888, 2013). "At both time points post-infection, the level of IL-10 expression was reduced significantly (p<0.001) to approximately one-fifth of the control level." (PMID 24086786, 2013). "It is likely that type I IFN also directly induces IL-10 production in macrophages at the early time points after infection." (PMID 24244162, 2013). "Our results from in vitro infection suggested that IL-10 affects the ability of B. abortus to survive inside macrophages." (PMID 23818855, 2013). "The differential effect on BMDC IL-12 family with minimal effect on IL-10 and IL-1β expression during infection with the two WT strains was a surprising finding." (PMID 23922820, 2013). "Microbes, including protozoa, nematodes, fungi, viruses, and bacteria, regulate host cell IL-10 expression to allow persistent infection." (PMID 23800014, 2013). "We found that macrophages are the main cellular source of IL-10 during infection and that the macrophages in these mice produce arginase as well as iNOS and are likely less efficient at controlling bacterial growth." (PMID 23613902, 2013). "Levels of IL-10 were high after 24 h and dropped to background levels 72 h after infection in WT mice." (PMID 23991239, 2013). "Quantification of IL-10 mRNA expression revealed that the highest amounts of IL-10 mRNA were expressed on day 2 post infection in the spleen." (PMID 24244162, 2013). "On day 14 days post infection the key Th2 cytokines IL-4 and IL-13 as well as anti-inflammatory IL-10 were produced in significantly higher amounts by mLN cells from infected mice in response to mitogen and parasite antigen." (PMID 24040152, 2013). "IL-10−/− mice were able to clear P. brasiliensis in liver and spleen and showed reduced tissue injury, as well as greater survival times after infection." (PMID 24205424, 2013). "Our results demonstrated an increased in Treg cell population in IL-10 KO animals compared to wild-type at 3 and 6 weeks post-infection." (PMID 24069337, 2013). "In this study, bone marrow-derived MØs and DCs displayed rapid IL-10 production in response to Bb, with levels apparent between 4-8 post-infection, and which continued to increase throughout the 48h period they were assessed." (PMID 24367705, 2013). "Maximal plasma IL-10 levels measured from the acute phase of infection correlated with the degree of plasma leakage, as determined by the pleural effusion index." (PMID 23800014, 2013). "The proapoptotic effect of type I interferon on lymphocytes negatively influences the murine host systemic immune response to L. monocytogenes following infection, likely via induction of IL-10." (PMID 23653659, 2013). "On the other hand, IL-2 and IL-4 levels in TNF-α KO mice were significantly higher than those of WT and IL-10 KO mice during mock infection and following JaOArS982 infections." (PMID 23940775, 2013). "It would appear unlikely that suppressive cytokines are secreted since the resolution of infection is similar between Cxcr5−/− and WT mice and IL-10 secretion has been shown to prolong the course of infection." (PMID 23365491, 2013). "In agreement with this, immunization by repeated infection and sub-curative treatment led to high levels of IL-5, IL-10, IL-12, IL-13, IFN-γ, and TNF compared to uninfected mice, where levels were very low or undetectable." (PMID 24180253, 2013). "IL-10−/− mice showed a significantly augmented reaction compared to normal mice at weeks 4 and 8 post-infection, suggesting a higher activation of the cellular immunity." (PMID 24205424, 2013).
infection (continued). "During infection, IL-10 facilitates immunosuppression and viral persistence by inhibiting the activity of Th1 and NK cells." (PMID 23398967, 2013). "Of note, severe pathology continued to be apparent weeks after anti-IL-10R administration was discontinued, suggesting that IL-10 produced early after infection is critical in the subsequent lesion development." (PMID 23555256, 2013). "In contrast, anti-inflammatory cytokine IL-10 showed a continuous increase over time, finally reaching significance at 36 h after infection (versus control P = 0.0015)." (PMID 23935245, 2013). "We observed that the percentage and total number of inflammatory monocytes after infection was reduced by around 40% in IL-10−/− mice when compared to the WT." (PMID 23554169, 2013). "At week 2 post-infection, IL-10−/− mice showed higher amounts of IgM as well as Th1- and Th2-related isotypes than WT mice." (PMID 24205424, 2013). "The production of tumor necrosis factor-α and interleukin-10 by MØ after infection with wild-type or mutant Mtb was examined using enzyme-linked immunosorbent assays." (PMID 23425360, 2013). "IL-10, which plays a major role in the negative regulation of the immune response, was also highest in group 1, confirming that infection with HP-PRRSV before PCV2 led to a more severe disease state." (PMID 23971711, 2013). "After REV infection, the expression levels of Th2 and regulatory cytokines (IL-4、IL-10 and IL-13) were drastically increased after 7 dpi, and moderately increased at 14 days and then up-regulated after 21 and 28 days following infection." (PMID 24358317, 2013). "In contrast, at later stage of infection IL-10 KO mice showed a reduction in granuloma numbers compared to wild-type animals which coincides with increased numbers of Treg cells and TGF-β expression in splenocytes." (PMID 24069337, 2013). "As observed before challenge, the ratio between IFN-γ/IL-4 and IFN-γ/IL-10, and between IL-12/IL-4 and IL-12/IL-10 indicated that vaccinated mice developed a specific Th1 immune response, which was maintained after infection in these animals (respectively)." (PMID 23573301, 2013). "S. mansoni egg antigens can downmodulate immune responses by activating Foxp3+ regulatory T cells and inducing IL-10, ameliorating the pathology of infection and reducing the response to other antigens in the lung." (PMID 23637937, 2013). "Nevertheless, our results contrast with those from other groups, who showed that IL-10 prevented mice of succumbing to some experimental infections, such as those with Plasmodium chabaudi chabaudi, Trypanosoma cruzi and Toxoplasma gondii." (PMID 24205424, 2013). "The IFN-γ and IL-10 levels of group 1 and group 2 were significantly elevated after infection as compared to day 0 (P < 0.05)." (PMID 24053449, 2013). "IL-10 levels are increased post-infection and this cytokine is assumed to have a key role in immunosuppression observed during the course of CSF disease." (PMID 23398967, 2013). "IL-10 mRNA was maximally induced during the first two days after infection and decreased afterwards in spleen, lung and liver." (PMID 24244162, 2013). "All monocultures and co-cultures containing monocytes produced ≥16 pg/mL IL-10 in response to infection." (PMID 24155979, 2013). "For in vivo studies, IL-10−/− and WT mice were i.t. infected with 1×106 Pb yeasts and studied at several post-infection periods." (PMID 24205424, 2013). "IL-10 has emerged as a key immunoregulator ameliorating the excessive Th1 responses that are responsible for much of the immunpathology during several infections." (PMID 24069337, 2013). "Small percentages of IL-10-producing cells were found inside the liver CD4+ T cells on day 7 of infection and CD4+ T cells producing only IFN-γ were also found in these suspensions." (PMID 24312297, 2013). "IL10SD mice exhibit significant changes in the immune response soon after infection indicating that IL-10 plays a role from the initial phase of the infection." (PMID 23555256, 2013).
infection (continued). "IL-10 is an important immunoregulatory cytokine; mice deficient in IL-10 display abnormally prolonged inflammatory responses, and infectious agents exploit the immunoregulatory actions of IL-10 to extend infection in the host." (PMID 23653658, 2013). "We examined profile of IFN-γ, a pathogenic Th1 cytokine of ECM, IL-4, a Th2 cytokine, TGF-β and IL-10, regulatory cytokines during the first week of infection." (PMID 23724100, 2013). "In a number of infections, the level and timing of IL-10 production is a pivotal factor in determining pathogen clearance versus pathogen persistence." (PMID 23561395, 2013). "That PBMC cultures at later time-points during infection which were less suppressed by Tci-L4-ES released more IL-10 seems somewhat contradictory to our previous findings that IL-10 signaling appeared to be an important mechanism of suppression." (PMID 23964850, 2013). "In agreement with previous studies we demonstrate here that DCs, B cells, macrophages, CD4+ and CD8+ T cells, but also neutrophils, NK cells and NKT cells produce IL-10 in the early phase of high dose LCMV Clone 13 infection." (PMID 24244162, 2013). "The results of these studies show that later stages of the infection are characterized by more dominant Th2 activity with elevated IL-4 and IL-10 levels and reduced IFN-gamma output in ConA- and antigen-stimulated splenocytes." (PMID 23555767, 2013). "The colonic gene expression of IL-10, IL-12p35, and IL-4 remained suppressed throughout the duration of infection alluding to the limited impact of colonic Treg, Th1, and Th2 cells in this process." (PMID 23469071, 2013). "IL-10−/− mice on a BALB/c background were able to control infection with L. major, and IL-10−/− mice on a C57BL/6 background, in contrast to their wild-type littermates, achieved sterile immunity to this parasite." (PMID 23825956, 2013). "During infection with intracellular parasites of the genus Leishmania, IL-10 undoubtedly plays an important role in disease development and pathogen persistence." (PMID 23825956, 2013). "IL-10 KO and wild-type mice were infected with B. abortus and 24 hours after infection serum IL-12, IL-17, TNF-α and IFN-γ levels were determined in these mice." (PMID 24069337, 2013). "We have demonstrated in this work that PPAR activation by agonists and cPLA2 inhibition by antagonist ATK are able to downregulate IL-10 expression throughout the course of infection with L. mexicana." (PMID 23555077, 2013). "Mean percentages ± SD of CD4+, CD8+ or CD19+ cells producing IFN-γ or IL-17 in 129 Sv/Ev or IL-10 KO splenocytes at one week post-infection with Brucella abortus." (PMID 24069337, 2013). "The role of IL-10 as an immunoregulatory cytokine in infection has been documented primarily in the context of chronic infections." (PMID 23509755, 2013). "IL-10 has been shown to inhibit immunopathological consequences in certain infection models, while its effect is detrimental in some other infections." (PMID 24386207, 2013). "The expansion but low IL-10 expression of FoxP3+ TREG cells was also observed in a separate study of the natural infection model." (PMID 23429492, 2013). "This co-culture model demonstrated synergistic IL-10 production effects between monocytes and uroepithelial cells following infection with UPEC." (PMID 24155979, 2013). "The critical role of IL-10 in modulating immune responses during chronic filarial infection has been shown most notably in animal models of infection." (PMID 24137161, 2013). "In the current study, it was found that infection of BALB/c mice with P. berghei K173 caused marked increases in plasma levels of pro- and anti-inflammatory cytokines including IL-5, IL-10, IL-12, IL-13, IFN - γ, and TNF." (PMID 24180253, 2013). "The inflammatory reactions and the production of Th1/Th2/Th17 cytokines were reduced at late phases of infection, paralleling the regressive infection of IL-10−/− mice." (PMID 24205424, 2013).
infection (continued). "Interleukin 10 (IL-10) is a key member of Cytokine, which regulates Th1/Th2 Cytokine balance, a major part of immune system against infection." (PMID 24032042, 2013). "This enhanced proinflammatory response observed in absence of IL-10 was accompanied by increased resistance to B. abortus infection with significantly reduced bacterial load in spleens of IL-10 KO mice over the course of infection studied." (PMID 24069337, 2013). "Infection was also associated with emergence of a population of splenic CD3ε+CD4+ T cells capable of producing both IFNγ and IL-10." (PMID 22911108, 2012). "The levels of IFN-γ were significantly higher on days 4 and 7 post infection in IL-10−/− liver leukocytes compared to WT." (PMID 22880122, 2012). "IL-10 is an anti-inflammatory cytokine secreted by many hematopoietic cells and has a central role in infection by limiting the immune response to pathogens in order to prevent damage to the host." (PMID 23071578, 2012). "The average IL-10 plasma levels of both the mild and severe disease groups increased after infection." (PMID 22533922, 2012). "By day 9 post infection the numbers of CD8+ T cells found in IL-10−/− livers were comparable to WT, whereas the numbers of macrophages, CD4+ T cells, and NK cells in these same IL-10−/− livers were still higher as compared to day 9 WT livers." (PMID 22880122, 2012). "IL-10 overexpression was shown to be an important mediator of allergic protection in different experimental models of infections or treatments with microbial products." (PMID 22952678, 2012). "Our data show that following infection with influenza virus, PBMCs from males produce more IL10 than females." (PMID 22768144, 2012). "During infection, induction of inhibitory immune pathways mainly mediated by IL10 production by DCs can also be observed." (PMID 22768144, 2012). "By this method, we observed increased concentration of IL-10 in the presence of genital HPV infections and particularly in cases of infections with only high-risk HPV." (PMID 22550593, 2012). "There is evidence from both experimental infections in mice, and from studies of infected people, that IL-10 plays a protective immunomodulatory role during schistosomiasis." (PMID 22291593, 2012). "This is either due to direct viral interactions with DCs or a result of indirect mechanisms, such as the production of IL-10 by monocytes during infection." (PMID 22754568, 2012). "A recent study focused on the genome-wide host transcriptional responses to CH-1a infection also showed increased expression of IL-10 in an in vivo infection model." (PMID 22909062, 2012). "Secretion of tumor necrosis factor alpha (TNF-α) and interleukin 10 (IL-10) was significantly induced during the infection of HLA-B27-transfected U937 cells with the mutants." (PMID 22470519, 2012). "IL-10 is an anti-inflammatory cytokine that plays an important role in the regulation of host immunity to infection." (PMID 22876184, 2012). "The numbers of NKp46+ TCRβ− NK cells in WT and IL-10−/− livers at 4 days post infection were nearly comparable." (PMID 22880122, 2012). "In order to regulate T cell mediated immunity during infections, in particular during chronic types of infection, IL-10 exerts pleiotropic direct and indirect suppressive effects towards different cell types of the innate and adaptive immune response." (PMID 22876184, 2012). "This interesting finding strongly provides a plausible significance of IL-10 specifically in curtailing an excessive inflammatory response induced by C. trachomatis during the early phase of infection before the development of adaptive immunity." (PMID 22529524, 2012). "Our data provide evidence that maternal STH infections predispose children to infections with STH parasites, and this effect was associated with elevated levels of IL-10 in newborn blood." (PMID 22848773, 2012).